NALCN (sodium leak channel, non-selective)
Description:
Voltage-sensing, pore-forming subunit of the NALCN channelosome complex, which regulates the resting membrane potential by depolarizing sodium leak currents. The NALCN channelosome complex is a voltage-gated ion channel responsible for the resting Na(+) permeability that controls neuronal excitability. The NALCN channelosome is constitutively active and conducts monovalent cations but is blocked by physiological concentrations of extracellular divalent cations. In addition to its role in regulating neuronal excitability, is required for normal respiratory rhythm, systemic osmoregulation by controlling the serum sodium concentration and in the regulation of the intestinal pace-making activity in the interstitial cells of Cajal (By similarity). The NALCN channelosome is also activated by neuropeptides such as neurotensin and substance P (SP) through a SRC family kinases-dependent pathway (By similarity). In addition, NALCN activity is enhanced/modulated by several GPCRs, such as CHRM3 (By similarity).
Synonyms: VGCNL1; bA430M15.1; CanIon; CLIFAHDD; IHPRF; IHPRF1; INNFD
Tractability: Small molecule: a structure with a bound ligand is known. Antibody: UniProt places it where antibodies can reach, with high confidence; its Gene Ontology location is reachable by antibodies, with high confidence; UniProt predicts a signal peptide or a membrane-spanning region.
Gene: Protein-coding gene on chromosome 13 (101,053,773 to 101,416,508, reverse strand). Ensembl gene ENSG00000102452.
Subcellular location: Cell membrane
Subcellular location (Human Protein Atlas): Cytosol; Microtubules; Primary cilium; Cytokinetic bridge; Mitotic spindle; Nucleoli; Plasma membrane
Pathways (Reactome):
Transport of small molecules: Stimuli-sensing channels
Gene Ontology:
Molecular function: protein binding; voltage-gated sodium channel activity; leak channel activity; monoatomic cation channel activity; sodium channel activity; monoatomic ion channel activity
Biological process: regulation of neuronal action potential; sodium ion transmembrane transport; calcium ion transmembrane transport; monoatomic ion transmembrane transport; positive regulation of synaptic transmission, cholinergic; positive regulation of synaptic transmission, GABAergic; potassium ion transmembrane transport; regulation of resting membrane potential; monoatomic ion transport; regulation of membrane potential; transmembrane transport
Cellular component: plasma membrane; voltage-gated sodium channel complex; membrane
Genetic constraint (gnomAD): Loss-of-function variants: 102 observed, 207.82 expected, observed/expected ratio (o/e) 0.49, 90% interval 0.42 to 0.58. The upper end of that interval is the gene's LOEUF score, 0.58, which puts it in group 2 of 6, group 1 being the genes least tolerant of losing a copy. Missense variants: 1,337 observed, 2,207.9 expected, observed/expected ratio (o/e) 0.61, 90% interval 0.58 to 0.63. Synonymous variants: 740 observed, 782.17 expected, observed/expected ratio (o/e) 0.95, 90% interval 0.89 to 1.
Homologues: Orthologues: chimpanzee NALCN (100% identical), macaque NALCN (99% identical), dog NALCN (99% identical), rabbit NALCN (99% identical), guinea pig NALCN (99% identical), pig NALCN (99% identical), rat Nalcn (99% identical), mouse Nalcn (99% identical), tropical clawed frog nalcn (96% identical), zebrafish nalcn (90% identical), Drosophila melanogaster na (56% identical), Caenorhabditis elegans nca-2 (47% identical), and 1 more. Paralogues in human: CACNA1C (18% identical), CACNA1D (17% identical), SCN2A (17% identical), CACNA1A (17% identical), CACNA1F (17% identical), CACNA1B (17% identical), SCN3A (17% identical), SCN8A (17% identical), SCN9A (17% identical), SCN1A (17% identical), CACNA1E (17% identical), CACNA1S (16% identical), and 14 more.
Diseases named in the same sentence as NALCN in open-access papers:
NALCN is named in the same sentence as 107 diseases in open-access papers, as found by Europe PMC text mining. Sharing a sentence is not in itself a finding about the gene and the disease. The quoted sentences say what the papers report.
developmental delay (24 papers, 2014 to 2025). "A de novo heterozygous missense variant in NALCN was detected in a female patient presenting with hypotonia, joint deformities, microcephaly, developmental delay, and ASD." (PMID 40558542, 2025). "Fam155a is a member of the NALCN channelosome, and the ion channel complex has been reported to be associated with intellectual disability and developmental delay." (PMID 40548375, 2025). "Previously, de novo NALCN variants were observed in 14 unrelated probands with congenital contractures of the limbs and face, hypotonia and developmental delay (CLIFAHDD, MIM#616266)." (PMID 36478354, 2023). "Many patients with NALCN mutations also develop serious clinical syndromes, such as severe hypotonia, speech impairment, and cognitive delay." (PMID 38273833, 2023). "Dominant pathogenic variants of NALCN are responsible for a syndrome refered to as congenital contractures of limbs and face, hypotonia and developmental delay (CLIFAHDD; OMIM #616266)." (PMID 31409833, 2019). "Mutations in the NALCN gene were recently reported in six patients with an autosomal-recessive syndrome characterized by severe hypotonia, speech impairment, and cognitive delay from two large consanguineous families." (PMID 24904279, 2014). "Considering the presence of distal arthrogryposis and global developmental delay, an arthrogryposis gene panel was arranged which showed a sequence variant in NALCN gene designated as c.3050T > G, which is predicted to result in the amino acid substitution (p.Ile1017Ser; NM_052867.2)." (PMID 37469362, 2023). "Indeed, case 17 with global developmental delay has a NALCN missense variant that matches with the CLIFAHDD syndrome (# 616266) overlapping patient’s phenotype, and case 18 was with a PTCH1 frameshift variant associated with Gorlin syndrome (#109400)." (PMID 33337535, 2021). "Pathogenic NALCN variants in humans are associated with severe hypotonia, speech impairment, cognitive delay, chronic constipation, and facial dysmorphism reminiscent of infantile hypotonia with psychomotor retardation and characteristic faces (IHPRF, OMIM #615419)." (PMID 33167491, 2020). "Recessive mutations in NALCN cause infantile hypotonia, developmental delay, and retardation." (PMID 31834878, 2019). "Another example is the identification and characterization of a dominant mutation in NALCN, which encodes a cation channel, causing intellectual disability, ataxia, and arthrogryposis —a gene previously associated only with a recessive condition with developmental delay and hypotonia (MIM# 615419)." (PMID 28874452, 2017). "Mutations in NALCN are associated with neuromuscular disorders including severe hypotonia, infantile neuroaxonal dystrophy (INAD), congenital contractures, cognitive delay, autism, epilepsy, bipolar disorder, and cardiac/respiratory problems." (PMID 39773880, 2025). "The gene mutations are associated with severe developmental delay, facial dysmorphism and mental retardation, reduced cognitive ability (KCNJ6, NALCN)." (PMID 35205240, 2022). "NALCN pathogenic variants have been associated to Neuroaxonal Dystrophy (INAD) patients, as well as to patients with severe hypotonia, speech impairment, cognitive delay, epilepsy, and mental disability." (PMID 33557955, 2021). "Variants in NALCN (sodium leak channel, non-selective) have been implicated in Infantile Hypotonia with Psychomotor Retardation and Characteristic Facies-1 (IHPRF1), an autosomal recessive condition characterized by moderate-severe hypotonia, developmental delay, and distinctive facial features." (PMID 41153369, 2025). "Mutations in NALCN or UNC80 are related to a group of diseases named “NALCN channelopathies”, which are characterized by infantile hypotonia, psychomotor retardation, characteristic facies, congenital contractures of the limbs and face, and developmental delays." (PMID 35482723, 2022).
developmental delay (continued). "Indeed, mutations in the NALCN gene were identified in Infantile Neuroaxonal Dystrophy (INAD) patients, as well as in patients with an Autosomal Recessive Syndrome with severe hypotonia, speech impairment, and cognitive delay." (PMID 24904279, 2014).
Intellectual disability (9 papers, 2017 to 2025). "Domains in UNC80, which are mutated in individuals with intellectual disability, interact to achieve the dendritic localization of NALCN complex." (PMID 32620897, 2020). "Gain-of-function mutations in the human NALCN gene cause encephalopathy and severe intellectual disability." (PMID 31601786, 2019). "In particular, UNC80 mutants truncated at the C-terminal end retain the protein’s somatic function, but lack dendritic localization and cause severe intellectual disability, suggesting the importance for the proper regulation of dendritic resting membrane potential through the NALCN channel." (PMID 32620897, 2020). "NALCN increased neuronal excitability and modulated a number of physiological functions, including respiratory rhythms in mice, locomotion of C. elegans, hypotonia, growth retardation, and the intellectual disability of NALCN mutant children." (PMID 34512260, 2021). "Mutations in the gene sodium leak channel non-selective (NALCN), which is involved in the control of neuronal excitability, can lead to speech impairment and intellectual disability in humans." (PMID 29609558, 2018). "To date, the C. elegans model aided the characterization of a novel gain-of-function mutation in Sodium Leak Channel Non-selective (NALCN) identified in a girl with intellectual disability, episodic and persistent ataxia, and arthrogryposis." (PMID 39339713, 2024).
CLIFAHDD syndrome (8 papers, 2020 to 2025). "Background/Objectives: CLIFAHDD syndrome (OMIM # 616266) is a rare neurodevelopmental disorder caused by mutations in the NALCN gene." (PMID 41153398, 2025). "In this paper, we report CLIFAHDD syndrome in a 14‐year‐old male patient with a novel variant in NALCN gene." (PMID 37469362, 2023). "Notably, the disruption of the NALCN gene is associated with two distinct conditions: the autosomal dominant CLIFAHDD syndrome and the recessive IHPRF1 (OMIM #615419), which presents with infantile hypotonia, psychomotor retardation, and characteristic facial features." (PMID 41153398, 2025). "Two years after the introduction of the KD, a NALCN (sodium leak channel, non-selective) gene mutation was perceived compatible with congenital contractures of the limbs and face with hypotonia and developmental delay syndrome (CLIFAHDD syndrome)." (PMID 31991539, 2020).
epilepsy (7 papers, 2014 to 2025). A brain disorder characterized by episodes of abnormally increased neuronal discharge resulting in transient episodes of sensory or motor neurological dysfunction, or psychic dysfunction. "Considering the importance of the NALCN channel complex in setting the resting membrane potential of neurons, the NALCN channelosome gene mutations are clear candidates for epilepsy." (PMID 24904279, 2014). "Previous studies have shown that mutations in the NALCN gene are associated with many neurological diseases, such as infantile hypotonia, severe mental retardation, psychomotor retardation, and epilepsy." (PMID 37569281, 2023). "In addition, NALCN gene may be a susceptibility locus for a variety of diseases, including alcoholism, alzheimer’s disease, autism, bipolar disorder, cardiac disease, epilepsy and schizophrenia." (PMID 37152978, 2023). "Moreover, the NALCN gene may serve as a susceptibility locus for several diseases, such as alcoholism, Alzheimer’s disease, autism, bipolar disorder, cardiovascular conditions, epilepsy and schizophrenia." (PMID 40013144, 2025). "Based on the potential implication of NALCN channel in human physiology and diseases, its pharmacological targeting might also be relevant to treat epilepsy, bowell motility disorders, osmoregulation disorders and psychiatric disorders." (PMID 24904279, 2014). "In addition, genes encoding NALCN, NLF- 1, UNC-79, and UNC-80 proteins may be susceptibility loci for several diseases including bipolar disorder, schizophrenia, Alzheimer's disease, autism, epilepsy, alcoholism, cardiac diseases and cancer." (PMID 24904279, 2014). "Thirty-five patients manifested epilepsy without any other comorbidity and seven of them (20.0%) carried variants in six genes, namely KCNQ2, NALCN, PAK3, PRRT2, SCN1A, and SLC2A1 that are among the well-known genes causing epilepsies or syndromes including epilepsy." (PMID 36035117, 2022).
schizophrenia (5 papers, 2014 to 2025). A major psychotic disorder characterized by abnormalities in the perception or expression of reality. "SNPs annotated to genes previously associated to obesity traits (LINGO2, NELL1) and neurological disorders (schizophrenia (ACSM1, KIF26B, NALCN)), and alcohol and nicotine dependence (LINGO, SH3BP5) were found among Prudent reported dietary pattern score associated-SNPs." (PMID 28644415, 2017).
alcoholism (4 papers, 2014 to 2025). "One single nucleotide polymorphism (SNP) in NALCN has been found to strongly associate with the high risk of alcohol dependence." (PMID 34335164, 2021). "A recent GWAS performed in 118 European-American families (2322 individuals) demonstrated a significant linkage of SNP rs17484734, located in the NALCN gene, and high-risk of alcohol dependence." (PMID 24904279, 2014). "This study may provide novel insights into the mechanism of alcohol actions, and studies of NALCN gene in humans may lead to a better understanding of alcoholism and its treatment." (PMID 34335164, 2021).
colorectal cancer (4 papers, 2017 to 2023). A primary or metastatic malignant neoplasm that affects the colon or rectum. "The authors found NALCN loss-of-function variant enrichment in human gastric and colorectal cancers and used murine models to demonstrate the deleterious effects with NALCN deletion or treatment with a NALCN channel blocker." (PMID 37789421, 2023). "It was found that colorectal cancer (CRC) displayed the highest frequency of NALCN gene alterations, with mutation as the primary type." (PMID 37152978, 2023). "In gastric and colorectal cancers, there was an enriched presence of loss-of-function mutations of NALCN." (PMID 37152978, 2023). "Among 10,022 human cancers, NALCN loss-of-function mutations were enriched in gastric and colorectal cancers." (PMID 36175792, 2022). "There is evidence that these three genes (FAM123A, CNRIP1 and NALCN) are associated with the risk of colorectal cancer." (PMID 28410574, 2017).
Dystonia (4 papers, 2016 to 2021). An abnormally increased muscular tone that causes fixed abnormal postures. "Therefore, the British study came to the following conclusion: NALCN, whose encoded protein belongs to a Na+-leak channel, may be a plausible candidate gene for dystonia." (PMID 27239368, 2016). "Some genome-wide association studies (GWASs) and replication studies have revealed correlations between single nucleotide polymorphisms (SNPs) of the ARSG, BDNF, NALCN, OR4X2, KIAA1715, and OR4B1 genes and dystonia." (PMID 35273550, 2021). "The NALCN protein interacts with UNC80 and pathogenic variants in both genes have been associated to dystonia." (PMID 33557955, 2021). "The British GWAS might overvalue the positive effect of SNPs of the NALCN gene in dystonia." (PMID 27239368, 2016).
cervical dystonia (3 papers, 2016 to 2021). "NALCN deficiency has been associated to channelopathies and cervical dystonia." (PMID 33557955, 2021).
glioblastoma (3 papers, 2022 to 2025). The most malignant astrocytic tumor (WHO grade IV). "Research indicates that NALCN expression is observed in certain cancers, including glioblastoma, non-small cell lung cancer (NSCLC), pancreatic cancer, small cell lung cancer (SCLC), and tumor-derived endothelial cells." (PMID 40013144, 2025). "NALCN is a voltage‐independent Na + channel that is expressed in many cancers, such as pancreatic cancer, nonsmall‐cell lung cancer, tumor‐derived endothelial cells, and glioblastoma." (PMID 35971319, 2022). "Studies reveal that NALCN is expressed in some cancers, such as glioblastoma, non-small cell lung cancer (NSCLC), pancreatic cancer, small cell lung cancer (SCLC) and tumor-derived endothelial cells." (PMID 37152978, 2023).
lung carcinoma (3 papers, 2017 to 2024). "However, due to the limited number of samples, the accuracy of NALCN promoter methylation as a prognostic or diagnostic biomarker in the plasma of lung cancer patients is expected to improve with the use of a sufficient number of samples." (PMID 39766220, 2024). "Then, to explore the effects of NALCN inhibition on lung cancer cytotoxicity, we performed a cell survival assay based on colony formation." (PMID 37139160, 2023). "An in vitro assay using A549 cells revealed that the NALCN inhibitor suppressed lung cancer cell proliferation and migration." (PMID 37139160, 2023).
small cell lung carcinoma (3 papers, 2023 to 2025). Small cell lung cancer (SCLC) is a highly aggressive malignant neoplasm, accounting for 10-15% of lung cancer cases, characterized byrapid growth, and early metastasis. "Studies show that NALCN is present in various cancers, including glioblastoma, non-small cell lung cancer, pancreatic cancer, small cell lung cancer (SCLC), and tumor-derived endothelial cells." (PMID 39766220, 2024).
and neck cancers (2 papers, 2023 to 2024). "NALCN was underexpressed in most cancers and was enriched with non-synonymous mutations in gastric, colorectal, lung, prostate, head, and neck cancers." (PMID 39766220, 2024). "NALCN is affected predominantly by non-synonymous mutations which enriched in colorectal, gastric, lung, prostate, head, and neck cancers." (PMID 37152978, 2023).
depression (2 papers, 2023 to 2024). "Future studies focusing on the functional property of NALCN in the cellular level of the VTA DA neurons under a state of depression are needed to clarify this issue." (PMID 39642080, 2024). "Recently, one study showed that NALCN modulates inflammation-induced depression by maintaining the activity of glutamatergic neurons in the ventral dentate gyrus (DG)." (PMID 37569281, 2023). "However, this does not completely exclude a possible contribution of NALCN to the altered functional activity of the VTA DA neurons which underlies the chronic-stress-induced depression-like behaviors." (PMID 39642080, 2024). "On the other hand, NALCN protein in the VTA was not altered in the CMUS male mice model of depression." (PMID 39642080, 2024). "We did not detect alteration of NALCN protein expression in the depression model of CMUS in the VTA tissue." (PMID 39642080, 2024).
gastric cancer (2 papers, 2024 to 2025). A primary or metastatic malignant neoplasm involving the stomach. "The expression levels of NALCN in tumor tissues, peripheral blood and gastric cancer cells lines from patients with GC were assessed using RNA sequencing, immunohistochemistry (IHC) staining and RT-qPCR." (PMID 40013144, 2025). "However, there is a paucity of experimental studies specifically addressing the relationship between NALCN and immune cell infiltration in gastric cancer (GC)." (PMID 40013144, 2025).